TNF (tumor necrosis factor)
Diseases named in the same sentence as TNF in open-access papers (continued):
Sharing a sentence is not in itself a finding about the gene and the disease.
infection (continued). "Necroptosis, a cell death mechanism involving TNFα stimuli, appeared in both organotypic cultures, consistent with the uncontrolled expression of TNFα and high levels of MLKL mRNA we found over the 4 days of infection in both the lungs and brainstem, compared to non-infected cultures." (PMID 34608167, 2021). "Even though we were not able to detect any TNF-α in the lungs after H1N2 inoculation in a previous study, others have reported that swIAV infection could lead to an increase in TNF-α concentration in the lungs." (PMID 34834975, 2021). "In addition, level of TNF-α is higher in patients with elevated HHV-6 load than without it (p = 0.028), also in comparison with patients without infection (p = 0.019)." (PMID 32403392, 2020). "Therefore, although the absence of T-bet results in defective CD4+ Th1 responses, TNF-α production is still maintained in these cells and CD8+ T cells are still able to produce significant levels of IFN-γ after STm infection." (PMID 32591391, 2020). "The infection with T. gondii increased the IFN-γ and TNF levels systemically, irrespective of whether or not the animals were treated with DFO or FeSO4." (PMID 32295126, 2020). "Although anti-TNF therapy agents such as infliximab and adalimumab are broadly used in patients with IBD, the outcome is not always successful and adverse effects such as infections frequently occur." (PMID 33519819, 2020). "Remarkably, infection with WT and pepP complemented strains, but not with ΔpepP resulted in increased concentrations of nitric oxide, IFN-γ, and TNF in mesenteric lymph nodes (MLN) (p < .05–0.001), and similar differences were obtained for IFN-γ and TNF levels in ileal biopsies (p < .01–0.001)." (PMID 32584649, 2020). "In contrast, in SP-A2 mice, the NFκB complex does not appear in the TNF node pathway and the IKK complex appears to be directly activated by BCL10, the expression of which was similar in males and females in SP-A2 and KO male 6 h post-infection." (PMID 32670284, 2020). "Anti-TNF-α-treated mice did not lose any weight during the first 5 days of RSV infection, in contrast to the isotype control group, which lost weight immediately following infection." (PMID 32071269, 2020). "Effective control of this infection requires not just the action of antibodies specific for the parasite's variable surface glycoprotein (VSG) coat antigens, but also a pro-inflammatory immune response mediated mainly by IFNγ, TNF, and NO." (PMID 32655552, 2020). "Therefore, although several experimental models have demonstrated TNFα-mediated osteoclastogenesis in the absence of RANK or RANKL, their relevance to the context of infection, which induces a plethora of osteoclastogenic stimuli, including RANKL, is unclear." (PMID 32987689, 2020). "However, the absence of TNFα, TNFβ, and MIP-1β production suggests that MOPV- and LASV-infection did not lead to the complete activation of pDCs, in contrast to that induced by the TLR7 and TLR8 ligand R848." (PMID 30901952, 2019). "Spleens of both the resistant and sensitive lines did not express leptin mRNA and lowly expressed LEPR mRNA, regardless of infection by MDV, while mRNAs of TNF and TNFR1 were induced in the spleens of both sensitive and resistant lines (TNF, 10- and 3-fold; TNFR1, 2- and 1.5-fold, respectively)." (PMID 31514326, 2019). "L. amazonensis infection also increased the levels of TNF-α and IL-1β, and MPO activity in the ipsilateral, but not contralateral paw tissue of infected mice when compared to control non-infected animals at day 40 after the infection (p < 0.05)." (PMID 31138231, 2019). "Similarly, at day 84 post-infection, no clear difference was observed in the concentration of IFN-γ, IL-1β, TNF-α, IL-12, IL-6, IL-10 and IL-4 in the both groups of mice." (PMID 31801478, 2019).
infection (continued). "Furthermore, the levels of interleukin (IL)-2, IL-4, IL-6, IL-22, and interferon (IFN)-γ, but not that of tumor necrosis factor alpha (TNF-α), IL-10, and IL-9, increased to their highest levels at day 4 post-infection and decreased thereafter." (PMID 31711531, 2019). "Our data suggest that higher levels of TNF- α between days 4 and 11 post-infection were responsible for this imbalance, whereas a number of field studies attribute this imbalance to lower levels of IL-10 in SMA rather than an increase in TNF-α46,75." (PMID 31831787, 2019). "While this indicates that sustained early TNF and CXCL1 are not due to increased bacterial burden at this timepoint, there have been reports of increased or decreased bacterial load in Ifnar1-/- mice in longer term infection models." (PMID 31385572, 2019). "However, at 6 weeks post-infection, rabbits infected with the clinical Mtb isolate CDC1551 had reduced TNF-α levels, concomitant with a reduced bacterial count, and no clinical signs of disease progression." (PMID 32010638, 2019). "At three months post-infection with low dose EBV, serum levels were biased towards proinflammatory cytokines and chemokines like TNFα, IL-8, and IL-6, while IFNγ and IL-10 were not significantly elevated, in contrast to what we observed after five weeks of high dose EBV infection." (PMID 31145756, 2019). "Interestingly, Beijing-1585 infection also showed a lack of induction, or even reduced expression of inflammatory cytokines IFN-γ, IL-17a and TNF-α compared to H37Rv as early as 3 dpi." (PMID 31882653, 2019). "However, converse to what was seen in C57BL/6 mice, during early infection, female and castrated BALB/c expressed higher lungs levels of TNF, IFNG, IL12, iNOS, and IL17 than non-castrated males." (PMID 30619306, 2018). "In addition, no induction in TNF-α was detected in WT and PI3Kγ KO fibroblasts, while CXCL1 was induced by the infection in KO cells, although in lower levels." (PMID 29867955, 2018). "Antigen-specific CD8+ T cell response was evaluated in the early (7 days) and late (2 months) phase of infection by measuring IFN-γ and TNF-α production after stimulation with non-inflationary peptide M45, inflationary peptide M38, as well as OVA-derived peptide SIINFEKL." (PMID 29867968, 2018). "Finally, infection experiments using genetically pure TNF-negative C57BL/6 mice resulted in a progressive and ultimately fatal, infection despite a strong Th1 response which was characterized by a hyper-expression of IFN-γ and the presence of iNOS." (PMID 29403488, 2018). "Measurement of the concentration of inflammatory cytokines in cell supernatants allowed us to observe significant decreases in the level of IL-8, IL-1b, IL-6, TNF-alpha and IL-10 in cells treated with VPA before or after infection with DENV serotype 2, without affecting cell viability." (PMID 29986388, 2018). "The gene expression of TNFα, IFNγ and IL-10 within ‘ATL-like’ cells was higher in patients with non-malignant infection compared to ATL (p = 0.048, p = 0.031 and = 0.056 respectively) in keeping with relative frequencies of cytokine secreting cells by intracellular cytokine staining." (PMID 29444188, 2018). "During early infection, anti-CD45R staining revealed a massive infiltration of B lymphocytes in lungs of TNFKi- and KLH-vaccinated mice, lower infiltration with PBS, and a near absence of B lymphocytes in TNF−/− or etanercept-treated mice." (PMID 29184553, 2017). "The absence of TNFα secretion in MAVS KO cells correlated with their decreased level of apoptosis in response to SeV infection, and supplementation of MAVS KO cells with TNFα, but not IFNβ, significantly increased apoptosis upon infection with SeV HD or LD." (PMID 28986577, 2017). "However, at late times, depletion of macrophages did not reduce the amount of TNF-α detected, suggesting that AMθ are not a major source of TNF-α that late in infection." (PMID 27099308, 2016).
infection (continued). "The data do not support the hypothesis that TNF and G-CSF mainly mediate HSPC mobilisation after infection in ayu." (PMID 27306736, 2016). "However, synergism between infection and other endothelial stressors such as oxidized-LDL or TNF-α especially on endothelial cell (EC) death has not been investigated." (PMID 27124409, 2016). "We also compared the frequencies of splenic CD4effector (CD4+CD44highCD62Llow) cells in mice infected 20 days earlier, and we also observed that upon infection, CD4+ T cells expressing IFN-γ and/or TNF can be detected without ex vivo restimulation, as previously reported." (PMID 27128676, 2016). "However, when mice were analyzed on day 10 after infection, we observed that the frequency and total number of polyfunctional IFN-γ and TNF-α producing CD8 T cells did not increase in comparison to isotype-treated animals." (PMID 28066432, 2016). "Importantly, both IFN-γ/TNF-α/IL-2 and IFN-γ/TNF-α responses to infection at 3 WPI (data not shown) and 8 WPI exceeded (P < 0.05) respective responses to vaccination upon recall stimulation of long-term cultures with Ag85A/TB10.4." (PMID 27799930, 2016). "The Th1 cytokine profile, i.e. IFN-γ, TNF-α and IL-12, is crucial to eliminate Leishmania, while the development of a Th2 immune response with the production of IL-4, TGF-β and IL-10 favors parasite multiplication and fails to control the infection." (PMID 26485398, 2015). "Additionally, quantitative realtime PCR was performed to validate RNA-seq data and the transcript levels of cytokines/chemokines, such as CXCL10, CXCL11, IFN-γ, TNF-α and IL-24, were all up-regulated upon H5N1 and H5N8 infection (data not shown)." (PMID 26576844, 2015). "In addition, D39 infection did not induce significant phosphorylation of p38 MAP kinase (MAPK) (p>0.05), whereas significant (P<0.05) phosphorylation of p38 was induced by TNFα as early as 45min and a maximal response was observed by 2h with Nm-OM treatment." (PMID 26566142, 2015). "Additionally, we analyzed TNF-α production from CFTR–/– and WT-mice infected with either highly mucoid CHB756 or non-mucoid CHB1058 at 3 hours and 6 hours post-infection." (PMID 26469863, 2015). "Furthermore, unlike the mouse infection model, SLY produced long-term stimulation of TNF-α release from PBMCs isolated from human blood." (PMID 26167160, 2015). "TNF-alpha was in fact detected in the blood of all animals but it was produced in a higher amount in group A compared to the groups B and C, at 4 h post STM14028-infection, without significant differences within groups at 24 and 48 h post infection." (PMID 26441914, 2015). "Inhibition of MEK, P38 and JNK could impair the expression of TNF-α and IL-1β at the mRNA level, with the only exception that inhibition of JNK could not significantly decrease the mRNA of IL-1β during infection." (PMID 26317438, 2015). "The examination of mRNA transcripts in liver cells 24 h after infection confirmed fold variation increases of 5.8 and 4.8 times on average for IL-1 and COX-2, respectively, in P1G10 pretreated mice but not for TNF-α, IL-10, γ-IFN and iNOS, for which the results were comparable to untreated animals." (PMID 24757289, 2014). "Moreover, L. major amastigotes did not induce the production of the proinflammatory cytokine TNF and the chemokines CCL3 and CCL4, which is in contrast to the higher production during promastigote infection." (PMID 25294956, 2014). "Thus, there was a strong negative correlation between the amount of TNF-α+IL-2+ CD4 T cells induced by the vaccines and the level of bacteria in the lungs 6 weeks after infection (R2 = 0.93 and 0.75, and p<0.0001 for Ag85B and TB10.4, respectively)." (PMID 23977248, 2013). "Among the four groups (i.e., non-infection group, LTBI group, TB at diagnosis group, and TB under treatment group), inflammatory cytokines, including IL-6, TNF-alpha, and IFN-gamma decreased from the non-infection group to the LTBI group, and then increased in the TB patients." (PMID 23356448, 2013).
infection (continued). "Furthermore, of the cytokines whose secretion was elevated by 1,25D treatment after infection (CCL3, CCL4, CCL8, IL-8, and TNF-α), treatment did not induce their secretion from uninfected cells." (PMID 23762029, 2013). "Interestingly, at six weeks post infection in the lungs, there was also a negative correlation between IFN-γ+TNF-α+IL-2+ and IFN-γ+TNF-α+ CD4 T cells and bacteria levels." (PMID 23977248, 2013). "Thus, even when murine infection is initiated with MHB-grown Ft the inflammatory response to actively replicating (now, host-adapted) bacteria at 24 h fails to include TNF, IL-1β, and IL-6." (PMID 23554897, 2013). "Infection of epithelial cells resulted in significantly increased secretion of the neutrophil chemotactic CXCL8 and IL-6, but no secretion of monocyte chemotactic CCL2 or TNF-α was observed." (PMID 22058091, 2012). "The levels of IL-8, TNF-α, IFN-α, and FasL transcripts in AMs in all groups with dual inoculation of PCV2 and PRRSV were significantly increased regardless of the infection orders as compared with infection by PCV2 alone or PRRSV alone." (PMID 23009687, 2012). "Stimulation of IL-6, IL-1β, and IL-17, independent of ClpV-mediated TNFα production, suggests that the T6SS may play a role in recruiting immune cells to the site of infection." (PMID 23071529, 2012). "As the infection process results in activation of Toll-like-receptor (TLR) signalling, triggering the expression of pro-inflammatory cytokines, including TNFα, we sought to ensure TLR activation in the absence of infection by treating transfected cells with bacterial lipopolysaccharide (LPS)." (PMID 22952450, 2012). "Also, the local concentration of the pro-inflammatory cytokines TNFα and IL-1β and the chemokines KC and MIP-2 was not different between wild-type and Cd55-/- mice at 24 h and 48 h after infection (data not shown)." (PMID 21984892, 2011). "Massive lymph node enlargement has also been seen in wildtype but not TLR4 gene-targeted mice during infection with Salmonella typhimurium and others have shown a role for TLR-independent, TNF-independent or TNF-dependent involvement of mast cells in non-specific induction of lymph node enlargement." (PMID 21637808, 2011). "Interestingly, using the IL8 expression assay we found that infection with the escV mutant was sufficient to induce IL8 expression in HeLa cells, albeit not as strong as that induced by TNFα (data not shown)." (PMID 20126447, 2010). "We were not able to detect any TNF-α in porcine plasma and BALF before and after infection." (PMID 19383119, 2009). "In plasma and BALF TNF-α could not be detected, whereas variable levels of IFN-γ were found at pre- and post-infection times." (PMID 19383119, 2009). "However, preliminary data suggests that in patients who are already on anti-TNF treatment the IFN-γ response is significantly reduced and negative IGRA results should therefore not be interpreted as implying absence of infection." (PMID 18706526, 2008). "With the Xenogen system, infection with the VSV-G pseudotyped HIV-1 was also detected, demonstrated by an increase in the bioluminescence emitted from placental fragments stimulated with TNF-α compared to those without TNF-α treatment." (PMID 16796744, 2006). "Likewise, infection of TLR2-, TLR4-, MyD88-, TNFα-, and CYBB-knockout mice does not affect bacterial burden, yet abrogates inflammatory tissue lesions." (PMID 16485466, 2005). "Despite inducing robust secretion of proinflammatory mediators such as IL-6, IL-8, and TNF, RSV infection does not elicit a marked increase in IL-1β levels in bronchoalveolar lavage fluid, nasopharyngeal secretions, or systemic circulation during the early phase of infection." (PMID 41576161, 2026). "However, TNFα, secreted by T lymphocytes, does not exhibit significant changes post-MRV infection." (PMID 40366173, 2025).
infection (continued). "In the current study, the high CD38 expression in old murine BMMs after infection with oral pathogens was not directly correlated with the activation of NF-κB, PI3K, and MAPK protein kinases nor the amount of pro-inflammatory cytokine (IL-1β, IL-6, and TNF-α) released in old murine BMMs." (PMID 40649955, 2025). "However, the infection of human epithelial cells with C. trachomatis did not result in NFκB activation, and inhibiting NFκB activation in these cells did not sensitize to STS- or TNFα/CHX-induced apoptosis." (PMID 39065071, 2024). "Early fever and high levels of CRP and inflammatory cytokines IL-6, TNF-α, and IFN-γ, as seen in our LE patients in the absence of infection, strongly resemble cytokine release syndrome, which may result in multiorgan dysfunction involving the brain, lung, and kidney." (PMID 37626859, 2023). "We used qPCR to analyze 12 host-related genes, including those with no significant fold change (IL12A), modest (e.g. TNF, LMO1, IL10, CCL2, IL1B) or high fold change, including CXCL8 which was among the 50 identified to be most significantly dysregulated in monocytes as a result of infection." (PMID 36747074, 2023). "In addition, infection with the ATCC strain induced non-homogeneous nuclear translocation of p65 in GES-1 cells, consistent with a lesser degree of p65 phosphorylation with respect to TNF, as assessed with western blotting." (PMID 37894827, 2023). "However, our study showed a significantly decreased TNF-α production in CD4+, CD8+ T cells and CD14+ monocytes in TB, and HIV co-infected with TB had obviously decreased TNF-α production in CD4+, CD8+ T cells and CD14+ monocytes under a natural infection status without external antigen stimulation." (PMID 37483385, 2023). "In a more recent permissive BMDM infection model using the NMII strain, no polarization of infected BMDM toward classical or an alternative activation state was detected, and modest production of TNF-α and nitrite was observed, which is consistent with our findings." (PMID 35913176, 2022). "Co-stimulation of SARS-CoV-2 S protein with the TLR2 ligand PAM3csk4, increased significantly the expression of the inflammatory mediators CXCL5, PAI-1 and IFNα at 12 hours following infection, but could not change the decreased production of the pro-inflammatory cytokines IL8, IL6 and TNFα." (PMID 36389723, 2022). "Previous studies have reported that infection with an IFN-γ-producing strain of C. neoformans induces similar alteration of cytokine profiles in mouse lungs as observed in the present study, but this is not observed in mice infected with a TNF-α-producing strain." (PMID 35720283, 2022). "The immune response during first infection with SA11 was not affected by B-GOS administration and had no impact on second infection, but the prebiotic intervention significantly increased IFN-γ and TNF-α intestinal production after the second infection (p < 0.05)." (PMID 35626706, 2022). "The splenocytes’ release of TNF-α and IL-1β was increased by 69% and 224.8%, respectively (all, &p < 0.05) while IL-6 and IFN-γ release was not significantly changed when mice were prophylactically immunized with V2/4 vaccine before infection (vs. non-vaccinated/infected mice)." (PMID 34497271, 2021). "Finally, we found that while infection with non-treated PAO1 did not affect the expression of two key inflammatory cytokines, TNFα and IL-6, infection with zinc-exposed PAO1 significantly increased the expression of both TNFα (2-fold, p < 0.01) and IL-6 (3-fold, p < 0.01)." (PMID 34948118, 2021). "Interestingly, SAG, unlike LPS or TNFα, upregulated CD40 expression on DCs even after LD infection." (PMID 33370418, 2020). "Therefore, we quantified the production of cytokines produced by macrophages (IL-6, IL-10, TNFα, IFN-γ, GM-CSF and IL-1β□ in non-infected, Mtb-infection, HIV-infected and co-infected cultures over the course of an Mtb-infection using multiplex cytokine profiling." (PMID 31133636, 2019).